APOB (apolipoprotein B)
Diseases named in the same sentence as APOB in open-access papers (continued):
Sharing a sentence is not in itself a finding about the gene and the disease.
hepatoma (65 papers, 2007 to 2026). "To understand the global consequences of APOB gene deficiency, we employed CRISPR-Cas9 system to generate apoB-deficient human hepatoma Huh-7 cells (Ako cells)." (PMID 40712734, 2025). "In short, our studies establish new hepatoma cell lines that are deficient in apoB expression and retain other machinery needed for lipoprotein assembly and secretion." (PMID 40712734, 2025). "Previously, we reported the generation of MTP-deficient human hepatoma cells and showed that these cells were defective in lipid and apoB secretion." (PMID 40712734, 2025). "On the other hand, mutated APOB has been found to be associated with immune infiltration in hepatocellular cancer." (PMID 38243282, 2024). "Heterozygous, rare, predicted loss-of-function variants in APOB have been described in other patients with cryptogenic cirrhosis and suggested to contribute to severe disease, including predisposition to hepatocellular carcinoma development." (PMID 36937991, 2023). "In this context, high apoB was related to increased intra-ocular metastasis in a Chinese population, whereas dysfunctional apoB mutations were associated with 46% increased risk of poor hepatocellular carcinoma outcomes." (PMID 31936330, 2020). "Significant APOB alterations induced by somatic mutations (~10%) or downregulation by hypermethylation likely result in hepatocellular carcinoma by diverting energy into cancer-relevant metabolic pathways." (PMID 30206226, 2018). "Indeed, rare loss of function mutations in APOB segregate in families with liver steatosis and hepatocellular carcinoma and are enriched in case studies with this cancer." (PMID 38405802, 2024). "Downregulation of APOB is associated with development of hepatocellular carcinomas." (PMID 38029961, 2024). "Moreover, increasing evidence shows that high concentrations of plasma APOB are also associated with poor prognosis in patients with hepatocellular carcinoma and breast cancer." (PMID 31963743, 2020). "Additionally, mutations leading to APOB inactivation are correlated with the overexpression of oncogenic regulators and the downregulation of tumor suppressors, resulting in poorer survival outcomes in hepatocellular carcinoma." (PMID 39399493, 2024). "To test this, we screened a miR library to identify miRs that reduce apoB and increase apoA1 and identified a primate-specific miR, miR-541-3p, that reduces apoB and increases apoA1 secretion in human hepatoma cells." (PMID 39782688, 2025). "In vitro, miR-548p promotes the posttranscriptional degradation of ApoB mRNA and reduces ApoB secretion from human primary hepatocytes and hepatoma cells." (PMID 40429957, 2025). "Apolipoprotein B (APOB), a member of the apolipoprotein family, is linked to several cancers, including non-small cell lung cancer, hepatocellular carcinoma, breast cancer, colorectal carcinoma, and gallbladder cancer." (PMID 40696350, 2025). "This supports previous suggestions of a role of apoA- IV in TG secretion from the liver, by interacting with apoB as shown in rat hepatoma cells and in mice liver by infection with apoA- IV adenovirus." (PMID 40032158, 2025). "While ApoB is essential for initiating lipid recruitment into VLDL particles, our results highlight an important compensatory role for ApoE in preventing excessive TG accumulation in response to defective ApoB secretion in hepatoma cells." (PMID 40180213, 2025). "We provide evidence that miR-541-3p concurrently reduces apoB and increases apoA1 in human hepatoma cells by regulating 2 different TFs, Casz1 and Znf101." (PMID 39782688, 2025). "While increased expression of APOB has been observed in breast cancer, bladder cancer, and ovarian cancer, it is downregulated in other cancer types, including hepatocellular cancer, colorectal cancer, and gastric cancer." (PMID 39979869, 2025). "This compensatory response to ApoB dysfunction activates ApoE expression, at least partially through the upregulation of transcription in hepatoma cells." (PMID 40180213, 2025).
hepatoma (continued). "In this screen, we found that miR-615-3p reduces apoB secretion by 50% in human hepatoma Huh-7 cells." (PMID 39332527, 2024). "Here, we identified a novel miR-615-3p that interacts with human 3′-UTR of apoB mRNA, induces post-transcriptional mRNA degradation, and reduces cellular and secreted apoB100 in human hepatoma Huh-7 cells." (PMID 39332527, 2024). "There is further analysis of the diagnostic role of ApoB/ApoA1 ratio in differentiating HCC from LC or CHB and in combination with AFP, a common diagnostic marker for hepatocellular carcinoma." (PMID 38744926, 2024). "In this study, we continued our search for miRs that regulate apoB and identified miR-615-3p as a novel regulator of apoB expression in human hepatoma Huh-7 cells." (PMID 39332527, 2024). "A second ERAD chaperone, HSP90, was also implicated in ApoB degradation, with transfection of HSP90 into a rat hepatoma line, RH-7777 significantly increasing ApoB degradation." (PMID 35174209, 2021). "In this study, we investigated the effects of EA on the secretion of two apolipoproteins, apoB and apoA-1, from human HepG2 hepatoma cells." (PMID 34202121, 2021). "An in vitro experimental study showed that AA administration increased ApoB secretion by 171% in human hepatoma cells." (PMID 33924871, 2021). "TM6SF2 is shown to facilitate the secretion of TG-rich very low-density lipoproteins (VLDLs), and to a lesser extent, that of apolipoprotein B (APOB) in human hepatoma cell lines." (PMID 32776921, 2020). "When apoA-IV was restricted in the ER of McA-RH7777 rat hepatoma cells, apoB trafficking from ER to Golgi was dramatically reduced, resulting in decreased apoB secretion as well as TG secretion." (PMID 30959835, 2019). "ApoE and ApoB in gradients of hepatoma cells were detectable within a density range of 1.0856–1.0298 g/ml for Huh7 and 1.0898–1.0272 g/ml for Huh7.5 cells, respectively." (PMID 29497123, 2018). "Recent genome-wide analyses searching for genes connected to development of hepatocellular carcinoma, the most common type of liver cancer, have turned up some unexpected genes, such as the fat metabolism gene apolipoprotein A (APOB)." (PMID 30429453, 2018). "Decreased secretion of apolipoprotein B from hepatoma cells has been reported in the presence of pitavastatin, and pitavastatin was more potent than simvastatin or atorvastatin in inducing apolipoprotein A-I secretion." (PMID 24586502, 2014). "In order to assess the inhibitory effect of shApoB1, shApoB2, miApoB1 and miApoB2 constructs on endogenous ApoB expression the mouse hepatoma Hepa1-6 cell line was selected." (PMID 22827812, 2012). "Deficiencies in the transfer of lipids to the nascent ApoB in hepatoma cell lines leads to degradation of most of the Apo B produced." (PMID 22039521, 2011). "We show here that LPL efficiently inhibits cell infection with two HCV strains produced in hepatoma cells or in primary human hepatocytes transplanted into uPA-SCID mice with fully functional human ApoB-lipoprotein profiles." (PMID 22039521, 2011). "For example, the over-expression of APOBEC-1 in mouse livers led to liver dysplasia and hepatocellular carcinomas, a phenomenon that has been attributed to promiscuous editing of mRNAs other than APOB." (PMID 17233885, 2007). "To determine whether miR-615-3p regulates apoB protein levels, we expressed it in human hepatoma Huh-7 cells." (PMID 39332527, 2024). "Therefore, we evaluated the efficacy of theses miRs in reducing apoB secretion in Huh-7 human hepatoma cells by adding them to the media and analyzing their effects on apoB secretion." (PMID 35278429, 2022). "To test this hypothesis, we knocked down the expression of Surf4 in human hepatoma-derived cell lines, Huh7 and HepG2 that express and secrete both apoB and apoA-I." (PMID 34118252, 2021).
hepatoma (continued). "In this context, in the present study, we investigated whether EA also affects the secretion of lipoproteins (apoB and apoA-1) from the hepatocytes using a human hepatoma cell line, HepG2." (PMID 34202121, 2021). "Likewise, overexpression of AADAC resulted in significantly reduced intracellular triacylglycerol levels and apolipoprotein B secretion, as well as increased fatty acid oxidation in rat hepatoma cells." (PMID 34869349, 2021). "TM6SF2 silencing also inhibits APOB secretion in two human hepatoma cell lines." (PMID 32776921, 2020). "In HepG2 human liver carcinoma cells, ApoB and ApoE are induced by 24 to 48 h Estrogen treatments." (PMID 32170217, 2020). "We observed hypoxia-induced DENV replication in human hepatoma cells as well as in a human hepatocyte cell line retaining important features of normal hepatocytes, including the secretion of liver-specific plasma proteins (albumin, fibrinogen, apoB)." (PMID 30513781, 2018). "We observed that quercetin suppressed apoB expression in the human hepatoma HepG2 cells." (PMID 25875015, 2015). "Moreover, we found that SMS inhibition reduces apoB secretion in a human hepatoma cell line and reduces the activation of NFκB and p38, a MAP kinase, in bone marrow derived macrophages." (PMID 25032960, 2014). "However, one must keep in mind that HCVcc can be considered “incomplete” LVPs since they lack apoB, and human hepatoma cells such as Huh-7 produce apoB-positive lipoproteins predominantly in the LDL range, indicating a defect in VLDL secretion." (PMID 24278733, 2012). "Thus, secretome of the hepatoma cells is affected by APOB gene ablation." (PMID 40712734, 2025). "Moreover, the metabolic reprogramming via mutation or downregulation of hypermethylated genes, including apoB and albumin, was observed in hepatocellular carcinoma, which indicated that this genetic pattern of metabolism-related regulation was possible to promote the progression in malignant tumors." (PMID 36713523, 2022). "HepG2 hepatoma cells, in which the expression of TMEM199 and CCDC115 was silenced, and induced pluripotent stem cell (iPSC)-derived hepatocyte-like cells from patients with TMEM199 mutations showed markedly increased secretion of apolipoprotein B (apoB) compared with controls." (PMID 34626841, 2022). "Consistently, knocking out the expression of both ApoB and ApoE dramatically reduced HCV production in hepatoma cell lines, while individual knockouts had only mild phenotypes." (PMID 30871009, 2019). "Similar crescent-shaped accumulations of APOB and ADRP around lipids trapped within the ER membranes were also observed in human hepatoma cell line Huh7 cells treated with proteasome inhibitors." (PMID 31526472, 2019). "It was assumed for instance that ApoB was relevant for HCV morphogenesis in vivo and in primary hepatocytes but dispensable in cultured hepatoma cell lines." (PMID 30871009, 2019). "A human hepatoma cell line, Huh-7, was incubated with an ApoB-targeting ASO (ApoB-10177-BNA) at 100 nM for 24 h in the presence of CaCl2." (PMID 26101258, 2015). "We found that simultaneous inhibition of both ApoE and ApoB, but not inhibition of either alone, led to TG accumulation in hepatoma cells, indicating that both proteins function redundantly to control TG content." (PMID 40180213, 2025). "We show that the miR-30c-3p passenger strand can be modified and duplexed with native miR-30c-5p to augment delivery to hepatoma cells and to reduce apoB secretion without affecting apoA1 secretion." (PMID 35278429, 2022). "We show that these analogs significantly reduced apolipoprotein B secretion in Huh-7 human hepatoma cells and human primary hepatocytes without affecting apolipoprotein A1 secretion and cellular lipid levels." (PMID 35278429, 2022).
hepatoma (continued). "Importantly, these non-hepatoma cell lines are quasi devoid of the lipoprotein synthesis equipment as they only express minute amounts of MTTP, CIDEB, ApoB or other apolipoproteins." (PMID 30871009, 2019). "However, we found both ApoB and ApoE require nascent biosynthesis of TGs catalyzed by redundant activities of both DGAT1 and DGAT2 for their efficient expression and secretion by the hepatoma cells." (PMID 40180213, 2025). "In our risk model, ApoB-VLDL has a negative predictive role, which has already been reported to be involved in the regulation of the expression of multiple genes in the development of hepatocellular carcinoma." (PMID 40821786, 2025). "Indeed, this hepatoma cell line, like HepG2, secretes relatively dense, lipid-poor ApoB lipoproteins, unlike the buoyant VLDL secreted in vivo by the human liver." (PMID 22039521, 2011). "HepaRG cells, in contrast to the widely used Huh7 and HepG2 hepatoma cell lines, are non-transformed cells, and their metabolism closely resembles that of normal primary hepatocytes, characterized by a strong secretory activity (albumin) and secretion of vLDL (apoB ELISA)." (PMID 30567412, 2018).
ischemic stroke (58 papers, 2009 to 2026). A stroke disorder caused by obstruction of blood flow to the brain, due to thrombotic (local blood clot formation) or embolic (due to a blood clot or other material traveling from another site) event. "Mendelian randomization studies based on GWAS data have strengthened the causal link between LDL-C/apoB and ischemic stroke subtypes." (PMID 40863347, 2025). "Our study contributes to understand the potential contribution of apoA-I and apoB to the pathogenesis of ischemic stroke subtypes and highlights the potential clinical relevance of the apoB/apoA-I ratio in ICAS risk stratification and stenosis severity." (PMID 38978811, 2024). "In conclusion, our study provides evidence that the ApoB/ApoA-I ratio at the acute stage of ischemic stroke is independently associated with the development of PSCI at 3 to 6 months in patients with large artery atherosclerosis." (PMID 37960323, 2023). "Evidence suggests a stronger association of lipoproteins with ischemic stroke compared with hemorrhagic stroke and the ratio of apoB/A1 has been reported to be the best lipid predictor of ischemic stroke risk." (PMID 36900073, 2023). "The strength of this study lies in its pioneering discovery of a positive correlation between ApoB/ApoA-I levels and the risk of recurrence of first ischemic stroke, a correlation that is particularly significant in LAA stroke patients." (PMID 38274879, 2023). "Current smoking, ApoA1, ApoB, male sex and education level showed stronger associations with CE whereas age was preferentially associated with ischemic stroke." (PMID 34772344, 2021). "In the final model, current smoking, ApoB, male sex and ≤ 9 years of schooling were preferentially associated with incident CE as compared to ischemic stroke (p for equal association = 0.038, < 0.001, < 0.001, and 0.040, respectively)." (PMID 34772344, 2021). "The association of AA synthesis with IHD was attenuated to the null and the association of AA synthesis with ischemic stroke was partly attenuated after adjusting for ApoB or LDL-C." (PMID 33924871, 2021). "In Model 2, waist circumference, smoking, systolic blood pressure, DM, ApoB, age, sex, total leukocyte count, and neutrophil count were positively associated with risk of both CE and ischemic stroke." (PMID 34772344, 2021). "It was repeatedly demonstrated that elevated ApoB/ApoA1 ratio played a risk role in ischemic stroke." (PMID 32017458, 2020). "Among traditional cardiovascular risk factors, apolipoprotein B/apolipoprotein A1 (ApoB/ApoA1) ratio is recognized to have the strongest predictive value for ischemic stroke." (PMID 32017458, 2020). "A high ApoB/ApoA1 ratio has been considered as risk factors in ischemic stroke, carotid stenosis, and other vascular diseases, which was consistent with our present study in some degrees." (PMID 33614678, 2020). "The genetic findings presented here show that variation in PCSK9 is associated with lower circulating LDL-C and apoB concentrations, lower risk of MI and, with lesser confidence, the risk of ischemic stroke and coronary revascularization." (PMID 31664920, 2019). "The purpose of our research was to explore the effect of ApoB gene polymorphism on the genetic susceptibility to Ischemic Stroke in Chinese Han male population." (PMID 29416768, 2018). "The association between ApoB gene and genetic susceptibility to Ischemic Stroke was performed by the χ2 test, genetic model analysis and haplotype analysis." (PMID 29416768, 2018). "Two small case-control studies and a small cohort study of patients with Ischemic stroke found that elevated apoB was associated with an increased risk Ischemic stroke." (PMID 29416768, 2018). "Meanwhile, we also found that the risk of individuals carrying the ApoB rs693 “AA-AG” genotype had Ischemic Stroke risk of 1.52-fold of carrying GG genotype (OR=1.52, 95%CI: 1.00-2.30, p=0.047) under the dominant model." (PMID 29416768, 2018).